TYR (tyrosinase)
Diseases named in the same sentence as TYR in open-access papers (continued):
Sharing a sentence is not in itself a finding about the gene and the disease.
type 2 diabetes (17 papers, 2018 to 2025). "Digested liqueurs showed potent and low inhibition to α-glucosidase and α-amylase, respectively, enzymes related to diabetes type 2; and moderate inhibition to tyrosinase and acetylcholinesterase, enzymes linked with neurodegenerative diseases." (PMID 31744100, 2019). "Enzyme inhibition assays further highlight T. willdenowii’s strong activity against acetylcholinesterase (96.4%), as well as tyrosinase and α-glucosidase, suggesting therapeutic potential in the treatment of neurodegenerative diseases and type 2 diabetes." (PMID 39795376, 2025). "Tyrosinase and α-glucosidase enzymes are known as promising target candidates for inhibitors to control unwanted pigmentation and type II diabetics mellitus." (PMID 35281605, 2022). "Regarding the enzyme inhibitory potential of the extracts, two enzymes involved in type II diabetes and skin diseases, α-glucosidase and tyrosinase, were selected to evaluate the differences between different extracts." (PMID 36248411, 2022). "anatolica methanol and aqueous extracts showed strong antioxidant activity and inhibition of enzymes tyrosinase and α-amylase, involved in skin disorders and diabetes mellitus type II." (PMID 34070308, 2021). "Extracts can also be used as mixtures or as a natural resource of polyphenols that can inhibit enzymes tyrosinase and α-amylase to prevent skin disorders as well as diabetes mellitus type II." (PMID 34070308, 2021). "Thus, the inhibition of acetylcholinesterase, butyrylcholinesterase, tyrosinase, α-amylase, and α-glucosidase has been considered to mitigate the deleterious effects of type II diabetes and AD or as adjunctive treatment modalities." (PMID 29463056, 2018).
acne (16 papers, 2017 to 2025). An inflammatory process of the sebaceous glands which is characterized by comedones, nodules, papules and/or pustules on the skin. "It effectively inhibited acne-associated pathogens and reduced melanin synthesis and tyrosinase activity in α-MSH-stimulated B16F10 cells." (PMID 41465805, 2025). "A previous study on the ethanolic leaf extracts of five species from the Lamiaceae family demonstrated that they have anti-acne effects through tyrosinase inhibitory and antioxidant activity, suggesting potential for treating skin hyperpigmentation." (PMID 39421673, 2024). "Novel formulations, i.e., spirulina nanoparticles with chitosan, as well as components of facial masks and creams, contribute to inhibition of tyrosinase activity, thus acting against resistant bacteria in acne therapy." (PMID 39458962, 2024). "Azelaic acid is a tyrosinase inhibitor and is widely used in acne treatment for its comedolytic and antibacterial properties." (PMID 37510902, 2023). "Broussonetia kazinoki has been used as a traditional medicine for the treatment of burns and acne, and its extracts have been found to show tyrosinase inhibitory and anticancer activities." (PMID 35335241, 2022). "Thus, the fraction exhibited tyrosinase inhibitory activity, anti-inflammatory effects in LPS-stimulated macrophages, and anti-acne activity against Staphylococcus epidermidis, highlighting its multifunctional bioactivity profile." (PMID 41226796, 2025).
Nystagmus (15 papers, 2012 to 2025). Rhythmic, involuntary oscillations of one or both eyes related to abnormality in fixation, conjugate gaze, or vestibular mechanisms. "Clinical evaluation of the families segregating either TYR or OCA2 mutations showed nystagmus, photophobia, and loss of pigmentation in the skin or hair follicles." (PMID 22734612, 2012). "However, careful examination of all variants in our nystagmus panel revealed a homozygous TYR variant (c.1205G > A; p.(Arg402Gln)), which could explain the TID." (PMID 32744312, 2020). "Ophthalmological findings included nystagmus and photophobia, typical of defective tyrosinase function, along with mild strabismus—a less common but reported OCA1 feature." (PMID 40860304, 2025). "Albinism and temperature-sensitive variants (c (albino), cb (Burmese), and cs (Siamese)) in tyrosinase (TYR), the Color locus in cats, are associated with disruption of the optical chiasma, leading to strabismus and nystagmus." (PMID 32580512, 2020). "The mother of proband 18 has both nystagmus and foveal hypoplasia, yet does not have the same deleterious TYR mutation as her son." (PMID 28667292, 2017). "Similarly, we do not observe nystagmus or photophobia in golden monkeys nor the consistent absence of fovea development that was recently observed in a report of TYR and OCA2-linked albino rhesus." (PMID 37522525, 2023).
skin pigmentation disorder (14 papers, 2017 to 2025). A pigmentation disease that involves the zone of skin. "Terpenes and terpenoids sourced from fungi display the capability to inhibit tyrosinase, suggesting potential applications in addressing skin pigmentation disorders and cancers linked to melanogenesis dysfunctions." (PMID 38474692, 2024). "Tyrosinase, a key enzyme in melanin production, plays a significant role in skin pigmentation disorders." (PMID 40686102, 2025). "Tyrosinase inhibitors are of interest for cosmetic applications and the treatment of skin pigmentation disorders." (PMID 40141204, 2025). "In the present study, both SFRP and SFEP from S. fusiforme have strong antioxidant activity as well as TYR inhibitory activity in vitro, suggesting they have potential skin whitening properties and can be used to treat skin pigmentation disorders." (PMID 39593972, 2024). "Tyrosinase inhibitors block melanogenesis and take part in melanin production or distribution leading to pigmentation diseases." (PMID 34923888, 2022). "In turn, tyrosinase inhibitors can be used in cosmetics/pharmaceuticals as whitening agents and to treat skin pigmentation disorders." (PMID 35470749, 2022). "The enzyme tyrosinase inhibition abilities of all three oils were also assessed as a part of our efforts to find a natural treatment for hyper-pigmentation skin disorder." (PMID 28103929, 2017). "Hence, tyrosinase inhibitors are an appealing target in cosmetics formulations as well as skin pigmentation disorders treatments." (PMID 36547543, 2022). "Moreover, these extracts showed a remarkable ability to inhibit the enzyme cyclooxygenase-2 and to activate the melanogenic enzyme tyrosinase, indicating their potential against chronic inflammation and skin pigmentation disorders." (PMID 32962162, 2020). "Finally, we verfied that ENST00000606533, circ_0091223, and TYR mRNA could form a ceRNA network linked by miR-1291, it is suggested that ENST00000606533, circ_0091223, and miR-1291 may be novel targets in the treatment of skin pigmentation disorder." (PMID 33318297, 2020).
ocular albinism (12 papers, 2011 to 2025). Albinism affecting the eye in which pigment of the hair and skin is normal or only slightly diluted. "Optical coherence tomography (OCT) revealed abnormal foveal contour, and light fundus pigmentation raised suspicion of ocular albinism (OA), a diagnosis later confirmed by identifying pathogenic variants in the TYR gene." (PMID 40125119, 2025). "In addition, some studies found that WS type 2 in conjunction with ocular albinism (OA) may result from a digenic mutation mechanism including both a MITF mutation and the TYR(R402Q) hypomorphic allele or TYRP mutation." (PMID 33506017, 2021).
Hypertension (11 papers, 2017 to 2024). The presence of chronic increased pressure in the systemic arterial system. "Here, we also evaluated the serum level of cysteine, a downstream product of homocysteine, which is known as a tyrosinase inhibitor and participates in hypertension development, one of the components of metabolic syndrome." (PMID 39337683, 2024). "The incidence of hypertension induced by tyrosinase inhibitors ranges from 5 to 80% in a dose-dependent manner." (PMID 34552487, 2021). "They indicated that TYR, an enzyme specific in altering phenolic compounds, effectively combated arterial hypertension." (PMID 31572179, 2019). "Moreover, these compounds have the potential to show multiple biological activities, including anticancer, anti-inflammatory, anti-glycation, anti-tyrosinase, anti-hypertension, antithrombotic, anti-diabetic, and antimicrobial activities." (PMID 36005524, 2022).
skin hyperpigmentation (11 papers, 2017 to 2025). "Tyrosinase inhibitors are candidates for skin-whitening agents that are useful in cosmetics to counteract age-related skin hyperpigmentation, and they also have potential in the treatment of diseases associated with tyrosinase misregulated expression and/or activity, such as urticaria pigmentosa." (PMID 36840143, 2023). "The strong inhibition of tyrosinase (59.56 ± 3.35 mg KAE/particles) indicates possible applications for managing skin hyperpigmentation." (PMID 41304917, 2025). "Our findings highlight the potential of this MCE as an effective tyrosinase inhibitor for the prevention of UVB radiation-induced skin hyperpigmentation." (PMID 40806718, 2025). "As expected, the use of 3-isobutyl-1-methylxanthine (IBMX), an inducer of skin hyperpigmentation, led to an increase in both the melanin content and the activity of tyrosinase, a crucial enzyme involved in melanogenesis." (PMID 37960097, 2023). "One such example is the activity of thiamidol, a resorcinol-derived compound, which demonstrated potent activity on human tyrosinase and prominent efficacy in treatment of various skin hyperpigmentations in human subjects, while being inactive against mushroom tyrosinase." (PMID 34682255, 2021). "This study investigated the tyrosinase inhibitory activity of RVLE containing gallic acid, chlorogenic acid, epicatechin, rutin, and resveratrol which are effective for skin hyperpigmentation." (PMID 28660210, 2017).
Hermansky-Pudlak syndrome (10 papers, 2007 to 2025). Hermansky-Pudlak syndrome (HSP) is a multi-system disorder characterized by oculocutaneous albinism, bleeding diathesis and, in some cases, neutropenia, pulmonary fibrosis, or granulomatous colitis. "A necessity for early cataract surgery has been reported in some patients diagnosed with Hermansky-Pudlak syndrome, a distinct form of autosomal recessive tyrosinase-positive OCA40." (PMID 27141993, 2016). "OCA can be caused by TYR, TYRP1 or MATP gene mutation; GS may be caused by pathogenic variants in MYO5A, RAB27A or MLPH; at least nine subtypes of hermansky-pudlak syndrome (HPS), HPS2 caused by variants in AP3B1 which most closely resembles CHS." (PMID 28145517, 2017). "Hermansky-Pudlak syndrome (HPS) is a multisystem disorder that is inherited in an autosomal recessive manner and is characterized by tyrosinase-positive oculocutaneous albinism and a bleeding diathesis resulting from a platelet storage pool deficiency and absence of platelet dense bodies." (PMID 27459687, 2016).
uveal melanoma (9 papers, 1995 to 2024). A melanoma derived from melanocytes of the uveal tract. "As we previously detected, CHCs (gp100+/CD45+, or TYR+/CD45+) were readily identified in all uveal melanoma peripheral blood specimens, while CTCs (gp100+/CD45− or TYR+/CD45−) were found at low levels or absent in all patients." (PMID 36230539, 2022). "Based upon the use of gp100 to identify conventionally defined CTCs we employed antibodies against gp100 and tyrosinase, a second protein in the pathway to detect CHCs in patients with uveal melanoma." (PMID 36230539, 2022). "The aim of this study was to investigate the expression of melan-A and tyrosinase in uveal melanoma, and the correlation with radiation therapy or clinicopathological parameters." (PMID 17445277, 2007). "The aim of this study was to investigate the correlation between radiotherapy or clinicohistopathological parameters and the expression of melan-A and tyrosinase in uveal melanoma." (PMID 17445277, 2007). "Posteriorly, formalin-fixed, paraffin-embedded sections of uveal melanoma were studied for the expression of melan-A and tyrosinase." (PMID 17445277, 2007). "High expression of gp100, MART-1 and tyrosinase was found in the uveal melanoma lesions: 80% of the lesions displayed 75-100% positive tumour cells." (PMID 9820172, 1998). "Interestingly, TYR (the key enzyme for melanin production) shows specificity of expression in both cutaneous and uveal melanoma." (PMID 34199192, 2021). "Ocular pigmentation was shown to be correlated to the incidence of uveal melanoma and age-related macular degeneration and tyrosinase, the key enzyme for melanin biogenesis, was found to be a potential factor for developing early stages of age-related macular degeneration." (PMID 30038866, 2018). "Moreover, when tyrosinase and melan-A are used together, 100% of the formalin-fixed, paraffin-embedded uveal melanoma samples tested positive for one of those markers." (PMID 17445277, 2007). "TyrBap1 KO mice were originally created to generate a uveal melanoma model since tyrosinase is expressed in neural crest–derived melanocytes, but no tumors were observed." (PMID 38690732, 2024). "The treatment of uveal melanoma cells with the agonist LNS8801 also induced the expression of melanin and differentiation markers such as MITF, which directs transcription of melanocyte specific genes required for melanin synthesis, and the downstream effector TYR." (PMID 37035582, 2023).
oculocutaneous albinism type 1A (7 papers, 2014 to 2026). Oculocutaneous albinism type 1A (OCA1A) is the most severe form of OCA, where no melanin is produced, and is characterized by white hair and skin, blue, fully translucent irises, nystagmus and misrouting of the optic nerves. "The combination of tools resulted in the indication of four, two and one nsSNPs as the most deleterious mutations in the TYR, TYRP1 and P proteins of the gene, which are associated with oculocutaneous albinism type IA (OCA1A), type III (OCA3) and type II (OCA2), respectively." (PMID 25794181, 2015). "Oculocutaneous albinism type IA (OCA1A) is a rare autosomal recessive disorder caused by variants in the TYR gene, resulting in complete loss of tyrosinase activity and absence of melanin production." (PMID 40860304, 2025).
prostate carcinoma (7 papers, 2001 to 2023). A carcinoma that arises from epithelial cells of the prostate gland. "MC1R Arg160/Arg160 homozygotes were at increased risk (P = 0.027, odds ratio = 1.94) while TYR A2/A2 homozygotes were at reduced risk of prostate cancer (P = 0.033, odds ratio = 0.48)." (PMID 11720436, 2001). "Enzymes such as elastase and tyrosinase, which are capable of inhibiting prostate cancer cells, are also present in the root extracts of T. erecta; these enzymes are known to be responsible for the transduction of adhesion and migration signals in tumor cells." (PMID 37894532, 2023). "The occurrence of prostate cancers in tyrosinase promoter/enhancer-driven transgenic mice prompted a detailed analysis of transgene expression in the prostate." (PMID 19079609, 2008). "These unanticipated observations suggest that prostate cancer is a late-onset tumor phenotype in RAS-activated GEM models engineered with this particular tyrosinase promoter-enhancer element." (PMID 19079609, 2008). "Other examples include arbutin (hydroquinone-O-beta-d-glucopyranoside), a tyrosinase inhibitor in A375 human malignant melanoma cells, and somatostatin, used in the treatment of advanced prostate cancer, which upregulated the expression of VDAC1 and VDAC2 in the LNCaP prostate cancer cell line." (PMID 28824871, 2017). "We studied 210 prostate cancer cases and 155 controls to determine whether vitamin D receptor (VDR, Taql and Fokl variants), tyrosinase (TYR, codon 192 variant) and melanocortin-1 receptor (MC1R, Arg151Cys, Arg160Trp, Val92Met, Asp294His and Asp84Glu variants) genotypes are associated with risk." (PMID 11720436, 2001).
breast carcinoma (6 papers, 2013 to 2023). "After transducing TYR into the breast cancer cell line MDA-MB-231, a stable line expressing TYR (231-TYR) was established and screened." (PMID 26483258, 2015). "We transfected TYR into human breast cancer cells (MDA-MB-231), naming the resulting cell line 231-TYR." (PMID 26483258, 2015). "Plasmid vector pc DNA 3.1-TYR was successfully constructed to express TYR, and stable breast cancer cell line expressing TYR was successfully selected by geneticin and named as MCF-7-TYR." (PMID 23508226, 2013). "Human breast cancer cells MCF-7 transfected with a plasmid that encodes TYR (named as MCF-7-TYR) and non-transfected MCF-7 cells were used as positive and negative controls, respectively." (PMID 23508226, 2013).
Erythema (6 papers, 2020 to 2024). Redness of the skin, caused by hyperemia of the capillaries in the lower layers of the skin. "For example, kojic acid, a synthetic tyrosinase inhibitor is widely used as a skin-whitening agent in cosmetics, later it was reported to cause several serious side effects, including erythema and contact dermatitis." (PMID 33260669, 2020). "Then, we randomized the wild-type TYR(+/+) mice into four groups, three individuals per group, to investigate the changes that occurred during skin erythema and melanin pigmentation in mice after UVB irradiation." (PMID 37032347, 2023).
microphthalmia (6 papers, 2003 to 2025). Congenital or developmental anomaly in which the eyeballs are abnormally small. "Microphthalmia-associated transcription factor acts in part via direct transcriptional activation of genes (tyrosinase, TYRP1 and TYRP2) required for pigment synthesis and also has a role in melanocyte survival and differentiation." (PMID 12966428, 2003). "Microphthalmia-associated transcription factor-M functions in melanocyte differentiation and survival, and directly activates the promoters of genes, including tyrosinase, that are required for pigment production." (PMID 12966428, 2003). "Microphthalmia-associated transcription factor, TRP-1, TRP-2, and TYR mRNA and protein levels were significantly increased after UVB irradiation in HEM cells." (PMID 35770009, 2022).
psoriasis (6 papers, 2011 to 2025). An autoimmune condition characterized by red, well-delineated plaques with silvery scales that are usually on the extensor surfaces and scalp. "Studies have demonstrated that tyrosinase can reduce the inflammatory response to psoriasis and improve symptoms by regulating immune system function." (PMID 40872627, 2025). "One hundred thirty-one compounds from Dendrobium plants have been reported to possess anti-inflammatory, antimicrobial, antioxidant, antiaging, anti-psoriasis, and tyrosinase-inhibitory activities." (PMID 33880726, 2021). "Tyrosinase activity may be disturbed in patients with psoriasis, resulting in an abnormal pigment metabolism." (PMID 40898481, 2025). "This may result from elevated proinflammatory cytokines in psoriasis-TNF, IL-17, IL-1 and IL-6, which are known to inhibit melanogenesis and specifically PKA, MITF, TYR and DCT." (PMID 34884858, 2021).
schizophrenia (6 papers, 2011 to 2025). A major psychotic disorder characterized by abnormalities in the perception or expression of reality. "In our study, many RB (CAT, GR, SOD-1, FRAP, AGEs, DITYR, NFK, TYR) were not related to schizophrenia." (PMID 34575267, 2021).
age (5 papers, 2022 to 2025). A temporal measurement of the time period elapsed since an identifiable point in the life cycle of an organism. "Importantly, while these studies support the mechanistic plausibility of α-synuclein–tyrosinase interactions, they do not yet establish any direct effects on age-related skin spots." (PMID 41515977, 2025).